CX3CR1 (C-X3-C motif chemokine receptor 1)
Diseases named in the same sentence as CX3CR1 in open-access papers (continued):
Sharing a sentence is not in itself a finding about the gene and the disease.
ischemic stroke (26 papers, 2014 to 2025). A stroke disorder caused by obstruction of blood flow to the brain, due to thrombotic (local blood clot formation) or embolic (due to a blood clot or other material traveling from another site) event. "Further analysis of protein expression changes revealed a reduction in CX3CR1 (CX3C chemokine receptor 1) in microglial VPS35-deficient cortex after ischemic stroke, implicating CX3CR1 as a potential cargo of VPS35 in this event." (PMID 31771656, 2019). "In ischemic stroke, CX3CR1 affects the volume of the infarcted area, BBB integrity, angiogenesis, and neurological recovery." (PMID 37452512, 2023). "In a model of ischemic stroke, CX3CR1 KO mice have larger damaged areas than WT and CCR2 KO mice 48 h after stroke." (PMID 37452512, 2023). "To the final aim, we worked with the Cx3CR1GFP/+ mice, in which GFP is expressed in brain microglia under control of the endogenous Cx3cr1 locus, widely used in ischemic stroke studies." (PMID 35454177, 2022). "For instance, Liu and colleagues utilized CX3CR1 siRNA in a bilateral common carotid artery stenosis (BCAS) rodents model and showed that the CX3CL1–CX3CR1 axis worsens the outburst of inflammation in ischemic stroke." (PMID 36397116, 2022). "After ischemic stroke, the number of CX3CR1(+) cells increased on days 3 and 7 in the injured brain, and those cells were infiltrating blood monocytes–derived macrophages, not resident microglia, which we have established using transgenic mice (CX3CR1GFP/+)." (PMID 33409730, 2021). "The relative percentage of total CX3CR1(+) cells from the brain decreased from 6 h (20.42 ± 2.64) to day 1 (6.87 ± 2.18) after ischemic stroke compared with the sham group (26.59 ± 1.37)." (PMID 33409730, 2021). "However paradoxical, these data are consistent with those reported from mice deficient for CX3CR1−/−, an immune regulatory receptor similarly important for maintaining CNS homeostasis, which demonstrates an early protective neuroinflammatory environment after ischemic stroke." (PMID 30777093, 2019). "At day 14, after ischemic stroke, CX3CR1+/GFP microglia were the major contributors of recruited cells to the ischemic lesion." (PMID 29866203, 2018). "Activation of the CX3CL1/CX3CR1 axis is neuroprotective in multiple neuroinflammatorydiseases, including ischemic stroke." (PMID 29692197, 2018). "Through a comprehensive literature search in PubMed databases through June 2025, we systematically elucidate the spatiotemporal regulatory mechanisms of the CX3CR1/CX3CL1 signaling axis across the full continuum of ischemic stroke and its central role in neural repair processes." (PMID 40722349, 2025). "We hypothesized that the CX3CR1 gene deletion could alleviate cognitive dysfunction after ischemic stroke." (PMID 38421089, 2024). "In this study, we explored whether CX3CR1−/− mice can mediate the NLRP3 inflammasome‐induced microglial pyroptosis after ischemic stroke." (PMID 38421089, 2024). "Collectively, these results indicate that the CX3CR1 gene deletion could enhance the AHN after ischemic stroke." (PMID 38421089, 2024). "Based on those results, we conclude that CCR2highCX3CR1low monocytes infiltrate shortly after an ischemic stroke and are then affected by specific cytokines to overexpress CX3CR1, which converts them into CCR2lowCX3CR1high macrophages attenuating an ischemic stroke." (PMID 33409730, 2021). "In addition, Sirt3 promoted microglial migration to the site of the lesion by upregulating the fractalkine receptor CX3CR1 in mice with ischemic stroke." (PMID 34630044, 2021). "However, the number of CD11bhigh and CX3CR1-double positive cells increased over time after ischemic stroke (% of CD11bhigh + CX3CR1: 2.88 ± 0.09 at 6 h, 2.43 ± 0.56 at day 1, 7.35 ± 0.94 at day 3, 12.66 ± 2.10 at day 7)." (PMID 33409730, 2021).
ischemic stroke (continued). "As shown by those antibodies, the number of Tmem119 and CX3CR1-double positive cells decreased significantly over time (% of Tmem119 + CX3CR1: 11.59 ± 3.75 at 6 h, 3.17 ± 0.50 at day 1, 2.47 ± 0.21 at day 3, 3.14 ± 0.59 at day 7) after ischemic stroke compared with the sham group (16.68 ± 0.27)." (PMID 33409730, 2021). "In addition, ischemic stroke-induced increase of CX3CR1 receptor levels is abolished in microglial VPS35-deficient mice, implicating CX3CR1 as a potential cargo of VPS35." (PMID 31771656, 2019). "Consistent with a previous study in ischemic stroke mice, we found that the expression of both CX3CL1 and CX3CR1 increased significantly in the hippocampus of rats and that this effect was mimicked by knockdown of miR-195." (PMID 32819407, 2020). "A previous study demonstrated that the expression of CX3CL1 and CX3CR1 is increased in rats early after ischemic stroke and that reducing the expression of CX3CL1 and CX3CR1 is beneficial for the recovery of neurological function." (PMID 32819407, 2020). "Attenuation of CX3CL1 signaling by CX3CL1 or CX3CR1 gene knockdown both significantly reduced infarct size, expression of IL-1β and TNF-α, and leukocyte infiltration in ischemic stroke models." (PMID 26860080, 2016). "Recently, it has been shown that the Ly6Clo CX3CR1+ monocytes did not impact functional recovery or severity of injury in a murine model of ischemic stroke." (PMID 25469644, 2014). "CX3CR1‐depleted monocytes alone may not be sufficient to protect the brain from ischemic stroke." (PMID 37452512, 2023).
liver fibrosis (26 papers, 2012 to 2025). "Conversely, studies investigating the protective role of CX3CR1 showed an increased risk of liver fibrosis with the loss of CX3CR1 in a model of hepatic fibrosis." (PMID 31316515, 2019). "Besides these findings, there are also data indicating a protective role of CX3CR1 since the loss of this receptor results in higher liver fibrosis in a model of hepatic fibrosis and increased accumulation of inflammatory monocytes in gliomagenesis." (PMID 28800592, 2017). "Ly6Chigh MO conversion to Ly6Clo anti-inflammatory macrophages with a restorative phenotype in murine hepatic fibrosis requires the upregulation of genes encoding molecules of the anti-inflammatory macrophage program, like CX3CR1, or with anti-fibrotic effects, like CD74." (PMID 25601191, 2015). "Furthermore, we only examined pro-inflammatory responses and hepatic granuloma formation during acute schistosomiasis; the impact of Cx3cr1 deficiency on hepatic fibrosis in the setting of chronic schistosomiasis, however, is yet to be elucidated, which should be a major focus for future studies." (PMID 26035381, 2015). "Further large-scale studies are needed to investigate the association between CX3CR1 polymorphisms and HCC development, comorbidities related to chronic liver disease, and the stage of hepatic fibrosis at baseline." (PMID 40733585, 2025). "BMS-935177, an orally active small molecule inhibitor, selectively blocks CX3CL1/CX3CR1 interaction and reduces liver fibrosis in experimental NASH models." (PMID 41269996, 2025). "Studies have shown associations between specific CX3CR1 SNPs and persistent HBV infection, viral load, and even the development of liver fibrosis." (PMID 40733585, 2025). "Splenectomy and adoptive splenic cells transfer allowed us to study the role of splenic CX3CR1+ cells and their subsets in the liver fibrosis." (PMID 38505603, 2024). "These cells further activated HSCs via CX3CR1/MyD88/NF-κB pathway and consequently promoted liver fibrosis and MAFLD progression." (PMID 38627387, 2024). "Thirdly, the authors proposed targeting Cx3cr1+Ccr2+MyD88+ Mo-macs-mediated liver fibrosis, which showed improvement upon treatment with the MyD88 inhibitor, ST2825, in Mettl14-KO mice." (PMID 38684673, 2024). "Splenectomy impairs the recruitment of CX3CR1+ cells to the fibrotic liver, uncovering the role of the spleen as a storage site of CX3CR1+ monocytes during liver fibrosis." (PMID 38505603, 2024). "The splenic CX3CR1+ cells and classical monocytes likely played a key role in promoting liver fibrosis progression." (PMID 38505603, 2024). "The oxidative stress condition provokes the inflammation and recruitment of Cx3cr1+Ccr2+MyD88+ Mo-macs that drive liver fibrosis via CX3CR1/MyD88/NF-κB/S100A pathway." (PMID 38684673, 2024). "Changes in behavior of hepatic CX3CR1+ cells when sensing splenic CX3CR1+ cells appeared to be prominent features of the inflammatory response in liver fibrosis." (PMID 38505603, 2024). "The photoconverted splenic CX3CR1+ KikRed+ cells were observed to leave the spleen, accumulate into the fibrotic liver and contact with hepatic CX3CR1+ KikGreen+ cells during hepatic fibrosis." (PMID 38505603, 2024). "Compared with Oil-treated mice, CCl4-induced liver fibrosis significantly increased the percentage (3.18% to 6.18%) and the number of CX3CR1+ cells (1.38×106 to 4.57×106) in the spleen of mice." (PMID 38505603, 2024). "Nevertheless, the possible involvement of splenic CX3CR1+ monocytes in the development of liver fibrosis remains uncertain." (PMID 38505603, 2024). "Splenectomy ameliorated liver fibrosis and decreased the number of CX3CR1+ cells in the fibrotic liver." (PMID 38505603, 2024). "In vivo research on the CX3CL1/CX3CR1 axis’s function in fibrosis revealed that CX3CL1/CX3CR1 signaling prevents macrophage-driven fibrogenesis in a hepatic fibrosis model." (PMID 37928902, 2023).
liver fibrosis (continued). "Since Ly6Clo macrophages are beneficial for hepatic fibrosis resolution, the number of Ly6Chi macrophages was significantly increased in CX3CR1-/- mice, followed by chronic inflammation and increased hepatic fibrosis." (PMID 35707538, 2022). "Conversely, the CX3CR1 fractalkine receptor acts to limit liver fibrosis by controlling the differentiation of monocytes and macrophages involved in fibrosis resolution." (PMID 25852818, 2015). "Taken together, these observations render the CCL2/CCR2 and the CX3CR1 pathways important targets for developing potential therapies for the treatment of liver fibrosis." (PMID 25852818, 2015). "Corroboration for involvement of Ly6C-lo monocytes comes from a study showing that deletion of the fractalkine receptor CX3CR1 (C–X3–C motif chemokine receptor 1), which is highly expressed on Ly6C-lo monocytes, inhibits resolution of hepatic fibrosis." (PMID 26618160, 2015). "Fractalkine was significantly up-regulated in the circulation upon disease progression, while CX3CR1 was down-regulated intrahepatically in patients with advanced liver fibrosis or cirrhosis." (PMID 23259611, 2012). "CX3CR1 and CX3CL1/fractalkine have been implicated in the liver fibrosis and their interaction prevents CCl4-induced liver inflammation and fibrosis in the mouse mainly because of the suppression on activation of kupffer cells (KCs) and HSCs." (PMID 22905138, 2012). "Taken together, CX3CR1 limits liver fibrosis in vivo by controlling differentiation and survival of intrahepatic monocytes." (PMID 23259611, 2012). "The fractalkine and its receptor CX3CR1 are protective in liver fibrosis." (PMID 39294573, 2024). "Furthermore, splenic CX3CR1+ classical monocytes (CD11b+ CD115+ CX3CR1low Ly6Chigh) exacerbated liver fibrosis via secreting proinflammatory and profibrotic cytokines." (PMID 38505603, 2024). "CX3CR1+ cells play a crucial role in liver fibrosis progression." (PMID 38505603, 2024). "Comparison of the migratory behavior of adoptive splenic CX3CR1+ cells and hepatic endogenous mobile CX3CR1GFP cells revealed that CX3CR1+ cells derived from different sources exhibited different migration characteristics and played a unique role in promoting the progression of liver fibrosis." (PMID 38505603, 2024). "This study reveals that splenic CX3CR1+ classical monocytes are a key driver of liver fibrosis via the spleen-liver axis and may be potential candidate targets for the treatment of chronic liver fibrosis." (PMID 38505603, 2024). "The current study showed that Cx3cr1+Ccr2+ Mo-macs expressed the adaptor Myd88 and activated the transcription of S100A4 via CX3CR1/MyD88/NF-κB signaling pathway, resulting in the activation of HSCs and thereby promoting the progression of inflammation and liver fibrosis." (PMID 38627387, 2024). "After contact with hepatic CX3CR1GFP cells, adoptive splenic CX3CR1+ cells and CX3CR1+ classical monocytes adopted slower speed and shortened displacement, which were important for trigging inflammatory responses and promoting liver fibrosis." (PMID 38505603, 2024). "A subset of splenic CX3CR1+ monocytes had characteristics of classical monocyte and migrated from the spleen and reached the fibrotic liver, causing behavioral changes of hepatic endogenous CX3CR1GFP cells and exacerbating liver fibrosis." (PMID 38505603, 2024). "In a model of reversible CCL4-induced liver fibrosis similar to the one used here, gene expression profiling has been done on liver infiltrating CX3CR1+ Ly6Chi monocytes at the necro-inflammatory phase (24 h) and their MoMF progenies at the early resolution phase (72 h)." (PMID 32296422, 2020). "Interestingly, increased serum CX3CL1 level correlates with chronic liver diseases, such as liver fibrosis, and CX3CR1 regulates the differentiation and survival of infiltrating monocytes in the liver of mice to limit fibrosis." (PMID 30305672, 2018).
liver fibrosis (continued). "Fourth, increasing evidence indicates that CX3CR1 is required for monocyte homeostasis and differentiation and regulates the fate of monocyte-derived cells in other inflammatory diseases such as cardiovascular disease and liver fibrosis." (PMID 24245985, 2013). "CX3CR1-/- developed greater hepatic fibrosis than WT animals in CCl4- and BDL-induced fibrosis." (PMID 23259611, 2012). "Apart from this mechanism, hepatic stellate cells are known to play the central role in hepatic fibrosis and apoptosis and inactivation of stellate cells as well as antifibrotic chemokines such as CX3CR1 could be evaluated in mini pigs model in future different studies." (PMID 40546987, 2025). "Therefore, to explain the modulation role splenic CX3CR1+ cells play in the progression of hepatic fibrosis, it is necessary to track the migration of splenic CX3CR1+ monocytes and study the spatial distribution and movement behavior of CX3CR1+ cells in the fibrotic liver." (PMID 38505603, 2024). "However, changes in the migratory behavior and spatial distribution of spleen-derived and hepatic CX3CR1+ cells in the fibrotic liver as well as their influence on the liver fibrosis remain unclear." (PMID 38505603, 2024). "Splenectomy, adoptive transfusion of splenocytes, in vivo photoconversion of splenic CX3CR1+ cells and intravital imaging were performed to study the spatial distribution, migration and movement behavior, and regulatory function of CX3CR1+ cells in liver fibrosis." (PMID 38505603, 2024). "In this study, the number of CX3CR1+ cells markedly increased in the CCl4-induced fibrotic liver and spleen, whereas splenectomy alleviated liver fibrosis and reduced the number of CX3CR1+ cells and their subsets (CX3CR1+ non-classical and classical Mon/Mφs)." (PMID 38505603, 2024). "In detail, Cx3cr1+Ccr2+ Mo-macs can be categorized into M1-like macrophages and S100A4-positive macrophages and then further activate hepatic stellate cells (HSCs) to promote liver fibrosis." (PMID 38627387, 2024). "To identify which subtype of splenic monocytes plays a key role in promoting hepatic fibrosis, we adoptively transferred splenic CX3CR1+ cells, classical monocytes and non-classical monocytes from fibrotic spleen into the CCl4-treated mice with splenectomy." (PMID 38505603, 2024). "Monocytes/macrophages lacking CX3CR1 exhibit increased cell death following liver injury, thereby sustaining inflammation, promoting persistent recruitment of inflammatory monocytes to the liver, and exacerbating hepatic fibrosis." (PMID 40918148, 2025). "Monocytes/macrophages lacking CX3CR1 undergo increased cell death following liver injury, which then perpetuates inflammation, promotes prolonged inflammatory monocyte infiltration into the liver and results in enhanced liver fibrosis." (PMID 23259611, 2012). "In the absence of CX3CR1, intrahepatic monocyte differentiation skews to favor inflammatory TNF-α- and NO-producing macrophages that result in inflammation persistence and enhanced liver fibrosis." (PMID 25852818, 2015).